DPP4 (dipeptidyl peptidase 4)
Diseases named in the same sentence as DPP4 in open-access papers (continued):
Sharing a sentence is not in itself a finding about the gene and the disease.
Hepatic steatosis (continued). "We previously reported that a DPP-4 inhibitor, des-fluoro-sitagliptin, prevented diet-induced adipose tissue inflammation and hepatic steatosis." (PMID 33105604, 2020). "Next, we investigated the impact of DPP-4 inhibition on lipoatrophy or hepatic steatosis in wild-type mice treated with OSI-906 for 7 days." (PMID 33105604, 2020). "The incidence of fatty liver in elderly diabetic patients decreased after DPP-4 inhibitors were used." (PMID 32368255, 2020). "Dipeptidyl peptidase 4 plays a vital role in the development of liver diseases, i.e., non-alcoholic fatty liver disease, hepatic steatosis and hepatocellular carcinoma." (PMID 32503418, 2020). "During DPP4 deficiency (inhibition or a knockout in mice), the sensitivity of pancreatic β-cells to this hormone may diminish, and as a result, insulin secretion may decrease, which, along with the action of glucagon and fatty liver disease, raises blood glucose levels." (PMID 33228030, 2020). "It has previously been shown that liver dpp4 expression is elevated in humans with ectopic fat accumulation in the liver and that hepatic dpp4 overexpression in mice is accompanied with liver steatosis, liver damage and hypercholesterolemia." (PMID 31794591, 2019). "Previous studies suggested that elevated hepatic dpp4 expression resulted in hepatic steatosis, inflammation, liver damage and hypercholesterolemia." (PMID 31794591, 2019). "Several studies have demonstrated that DPP-4 inhibitors can prevent and improve liver steatosis in diabetic mice or rodents fed a high-fat diet." (PMID 27462372, 2016). "We previously demonstrated that treatment with a DPP-4 inhibitor improved hepatic steatosis in both SL-fed and SO-fed βGck+/− mice." (PMID 26937254, 2016). "A recent study demonstrated that the DPP-4 inhibitor linagliptin alleviates hepatic steatosis and inflammation in a new murine model of NASH with a diabetic background independently of its glucose-lowering effect." (PMID 27462372, 2016). "The novel DPP4-inhibitor MK-0626 attenuates hepatic steatosis by enhancing AMPK activity, inhibiting hepatic lipogenic gene expression, increasing triglyceride secretion from liver, and elevating serum adiponectin levels." (PMID 26284071, 2015). "Furthermore, EGCG from green tea inhibited the expression and activity of dipeptidyl peptidase 4 (DPP4), which is closely linked to the progression of hepatic steatosis and liver damage." (PMID 40289935, 2025). "Moreover, serum levels of DPP-4 have been shown to correlate with the severity of hepatic steatosis, suggesting a direct link between DPP-4 activity, liver damage, and hepatic lipogenesis." (PMID 40243565, 2025). "Recent evidence in mice demonstrated that dipeptidyl peptidase-4 (DPP-4) inhibitors could improve the degree of hepatic steatosis and IR through AMPK-dependent and JNK-dependent inhibition of LECT2 expression." (PMID 38297351, 2024). "Additionally, it lowers blood DPP-4 activity, as hepatic steatosis is correlated with elevated DPP-4 levels in NAFLD patients." (PMID 39673064, 2024). "Furthermore, the clinical usage of DPP4 inhibitor therapies reveal improved hepatic steatosis and glucose tolerance." (PMID 37367914, 2023). "DPP4 is known to promote hepatic steatosis through increased fatty acid uptake into hepatocytes." (PMID 37367914, 2023). "Elevated circulating dipeptidyl peptidase-4 (DPP4) is a biomarker for liver disease, but its involvement in gluconeogenesis and metabolic associated fatty liver disease progression remains unclear." (PMID 36472923, 2023). "Of note, the overall improvement in hepatic steatosis is also found in patients treated with other classes of anti-diabetic drugs, like thiazolidinediones and dipeptidyl peptidase-4 (DPP-4) inhibitors, raising the question of steatosis improvement due to glycemic control." (PMID 35328527, 2022).
Hepatic steatosis (continued). "Interestingly, treatment with the DPP4 inhibitor des-fluoro-sitagliptin resulted in an amelioration of diet-induced visceral obesity and hepatic steatosis." (PMID 33538983, 2021). "Additionally, in human liver biopsy specimens from obese patients, DPP4 expression was positively correlated and DNA methylation was negatively correlated with stages of hepatic steatosis and NASH." (PMID 33143364, 2020). "However, the mechanisms responsible for the protective effects of DPP-4 inhibition on fatty liver are obscure." (PMID 33105604, 2020). "In contrast, DPP-4 inhibition with linagliptin improved OSI-906-induced hepatic steatosis." (PMID 33105604, 2020). "Previous studies showed that inhibition of DPP-4 prevents hepatic steatosis in animal models." (PMID 32937958, 2020). "The incidence of fatty liver in elderly diabetic patients decreased after using DPP-4 inhibitors." (PMID 32368255, 2020). "However, treatment with the siRNA targeting dpp4 resulted in a reduction of liver steatosis and expression of key genes in lipid metabolism." (PMID 31794591, 2019). "Transgenic rats deficient in dipeptidyl peptidase-4 (DPP4-), the enzyme that degrades endogenous GLP-1, have a threefold higher basal active GLP-1; they not only have lower hepatic fat, but are also protected against hepatic steatosis when fed a high-fat diet." (PMID 23236362, 2012). "Additionally, hepatic steatosis could be prevented in several different animal models by DPP4 inhibition." (PMID 26284071, 2015). "DPP4, one of the genes suppressed by MUN, is involved in Western-diet-induced hepatic steatosis through hepatic triacylglycerol and diacylglycerol accumulation." (PMID 35323646, 2022). "Additional effects of MES + HS with current DPP-4 inhibitor treatment are observed in FPG, L-FABP, and hepatic steatosis." (PMID 27759092, 2016). "DPP-4 inhibitors, despite their initial promise, have not consistently improved liver steatosis and fibrosis, resulting in their lack of recommendation for MASLD." (PMID 39860434, 2025). "DPP4 is highly expressed in the liver, while the expression and serum levels of DPP-4 are elevated in steatohepatitis patients, and also correlate with hepatic steatosis, fibrosis, and hepatocyte apoptosis, making DPP4i an attractive therapeutic option for patients with NAFLD." (PMID 37938366, 2024). "However, the potential benefits of DPP4 inhibitors on NASH, particularly on hepatic inflammation and fibrosis other than hepatic steatosis, are poorly understood." (PMID 37739179, 2023). "Patients with NASH have increased serum DPP-4 activity compared to controls and also increased hepatic staining of DPP-4 that correlated with hepatic steatosis and histopathological grade of NASH but were not correlated to each other." (PMID 32823659, 2020). "Although the investigations in vivo are still insufficient, the data suggest that DPP-4 inhibitors and GLP-1 receptor agonists may improve hepatic steatosis and suppress the progression of hepatic fibrosis." (PMID 26191473, 2015). "Twenty-one studies were considered, including three studies based on liver histology, showing that GLP-1 RAs and SGLT2 inhibitors decreased hepatic steatosis and steatohepatitis in NAFLD patients, while DPP-4 inhibitor therapy was not effective for patients with hepatic steatosis." (PMID 34199535, 2021). "Our findings support the non-canonical pleiotropic effects of DPP-4 inhibitors without a glucose-lowering effect and suggest the potential of DPP-4 inhibitors as a new treatment for fatty liver disease." (PMID 33105604, 2020). "On the contrary, sitagliptin, an oral dipeptidyl peptidase-4 (DPP4) inhibitor, in a recent RCT did not significantly reduce liver steatosis in prediabetic or diabetic patients with NAFLD." (PMID 31010049, 2019).
Hepatic steatosis (continued). "RDX8940 pharmacokinetics and effects on GLP secretion, insulin sensitivity, and liver steatosis were assessed in C57BL/6 mice fed normal or Western diet chow and given single or repeated doses of RDX8940 or vehicle, with or without dipeptidyl peptidase-4 (DPP4) inhibitors." (PMID 30605011, 2019).
pancreatitis (57 papers, 2010 to 2025). Inflammation of the pancreas. "Overall, the evidence in clinical trials supporting the risk of pancreatitis in DPP-4 inhibitors and GLP-1 analogs is weak due to sample size limitations." (PMID 40308779, 2025). "Given the potential risk of pancreatitis in diabetic patients using DPP-4 inhibitors, pre-existing risk factors for pancreatitis should be taken into account when prescribing this type of medication." (PMID 32938499, 2020). "In the present study, pancreatic disorders, including pancreatitis and pancreatic cancer, were associated with DPP-4 inhibitors and GLP-1 receptor agonists, which were consistent with results obtained via analysis of the FAERS." (PMID 26989609, 2016). "The putative association of DPP-4 therapy with development of pancreatitis and pancreatic cancer remains to be confirmed." (PMID 26075286, 2015). "DPP-4 inhibitors, compared with placebo or other treatment, were associated with a similar risk of cancer and pancreatitis, and with a reduced risk of MACE." (PMID 23710467, 2013). "Such timely interventions alleviate patient discomfort and may help prevent more severe complications, including pancreatitis, which are of concern in association with DPP-4 inhibitors." (PMID 40981239, 2025). "While some association exists between the occurrence of pancreatitis and dipeptidyl peptidase 4 inhibitors (DPP4i) and glucagon-like peptide-1 receptor agonists (GLP-1RA), there are only a few reports linking sodium-glucose co-transporter-2 inhibitors (SGLT-2is) with pancreatitis." (PMID 39036218, 2024). "Numerous challenges in development of DPP-4 inhibitors have been seen such as % yield of synthesized compounds, gastrointestinal problems, skin reactions and majorly high risk of developing pancreatitis have been observed experiencing severe pain in upper abdomen." (PMID 37570832, 2023). "DPP-4 inhibitors can cause severe adverse effects such as hypersensitivity reactions (Stevens–Johnson syndrome, anaphylaxis, bullous pemphigoid), infections, pancreatitis or intestinal obstruction." (PMID 34256874, 2021). "In these studies, the use of DPP-4 inhibitors increased the risk of pancreatitis." (PMID 29335646, 2018). "Although an efficient drug class for the treatment of T2D, recent data indicate that long-term administration of the GLP-1R agonists and DPP4 inhibitors may be linked to an increased risk of pancreatitis and pancreatic cancer." (PMID 25119717, 2014). "However, there is keen interest founded in development of novel DPP-4 inhibitor as some of the marketed drugs have adverse effects such as gastrointestinal problems, skin reactions and majorly high risk of developing pancreatitis have been observed experiencing severe pain in upper abdomen." (PMID 37570832, 2023). "We found that DPP-4 inhibitors may reduce the risk for mortality, hospitalization, hypoglycaemia and adverse events leading to discontinuation and may have little impact on pancreatitis suggesting that DPP-4 inhibitors have a better benefit–risk ratio than sulfonylureas in older patients." (PMID 35111291, 2022). "In addition, a previous study showing increases in number of pancreatic duct cells in response to incretin-based treatment suggested that DPP-4 inhibitors may be associated with pancreas-related safety issues, such as pancreatitis and pancreatic cancer." (PMID 33149182, 2020). "Also, the potential risk of pancreatitis has been added to the label of DPP-4 inhibitors." (PMID 31275243, 2019). "However, it remains unclear why DPP-4 inhibitors are associated with pancreatitis and GLP-1 agonists are not21." (PMID 29335646, 2018). "Although traditional DPP-4 inhibitors (e.g., sitagliptin) are relatively safe, rare adverse effects like pancreatitis and arthralgia persist." (PMID 40509444, 2025). "Incretin-based therapies (glucagon-like peptide-1 receptor agonists and oral dipeptidyl peptidase-4 inhibitors) are avoided because of concerns about pancreatitis." (PMID 40401174, 2025).
pancreatitis (continued). "We found that sitagliptin-related pancreatitis usually occurred approximately 6 months after drug initiation, while other DPP-4 inhibitors usually occurred at 3 months." (PMID 40308779, 2025). "The aim of this study was to compare the risk of developing pancreatitis between those using GLP-1 RAs and those using sodium-glucose transport protein 2 (SGLT2) inhibitors and dipeptidyl peptidase 4 (DPP-4) inhibitors." (PMID 38860168, 2024). "Observational studies examining the connection between pancreatitis and DPP-4 inhibitors, utilizing clinical databases from diverse countries, have produced conflicting outcomes." (PMID 39027329, 2024). "Within the DPP-4 inhibitors group, 58 patients were excluded due to a pre-existing diagnosis of pancreatitis before the index date." (PMID 39027329, 2024). "Given an increasing use of DPP-4 inhibitors to treat patients with T2DM in the real-world setting, potential pancreatitis risk has been of concern because of its consequent pharmacological mechanism of the pancreas." (PMID 37814306, 2023). "Since the introduction of GLP-1RA and DPP-4 inhibitors there has been some concern regarding the potential increase in pancreatitis and possibly pancreatic cancer with the incretin class of medications." (PMID 32308645, 2020). "Sitagliptin, Vildagliptin, Anagliptin, Saxagliptin, and Alogliptin are the main clinically used chemicals for human dipeptidyl peptidase-4 (DPP4) inhibition despite their side effects as pancreatitis, nausea, and anemia." (PMID 31661941, 2019). "Development of DPP-IVi from plant-based sources is on the increase due to the observed side effects such as pancreatitis, cardiovascular challenges, renal- and hepatotoxicity of clinically approved DPP-4 inhibitors." (PMID 31775302, 2019). "Pancreatitis and hepatitis have also been suspected to occur due to dipeptidyl peptidase-4 inhibitor (DPP4I) treatment." (PMID 30674350, 2019). "Fifty-three trials enrolling 20,312 and 13,569 patients for DPP-4 inhibitors and comparators, respectively, were included, reporting 176 malignancies, 257 MACEs, and 22 pancreatitis." (PMID 23710467, 2013). "No clinically relevant changes in laboratory immunologic parameters have been found in studies of DPP-4 inhibitors, and pancreatitis was reported at lower rates with the DPP-4 inhibitors compared with other oral antidiabetic agents." (PMID 22645689, 2012). "Although there are studies on whether DPP-4 inhibitors and GLP-1 analogs increase the risk of pancreatitis, few studies have focused on time to onset." (PMID 40308779, 2025). "The reported odds ratio (OR) of 0.93 with a 95% confidence interval (CI) of 0.51–1.69 indicates that there is no statistically significant increase in the risk of pancreatitis associated with DPP-4 inhibitors based on the available RCT data." (PMID 39027329, 2024). "Additional systematic reviews encompassing both randomized and non-randomized studies have similarly indicated that incretin therapy, that is, DPP-4 inhibitors, does not seem to be correlated with an elevated risk of pancreatitis in individuals with T2D." (PMID 39027329, 2024). "These all drugs falls under competitive inhibitors and founded to be responsible for about 70% of inhibition of plasma DPP-4 with some reported side effects such as nasopharyngitis, respiratory tract infections, headache and major setback is founded to be pancreatitis and hypersensitive reactions." (PMID 37570832, 2023). "Dipeptidylpeptidase-4 (DPP4) inhibitors and Glucagon-like peptide-1 receptor agonist (GLP-1RAs) are important treatments for T2D.These medicines may increase the risk of pancreatitis." (PMID 37467250, 2023). "However, currently available DPP-4 inhibitors have several adverse effects such as arthritis, pancreatitis, diarrhea, and congestive heart failure that limit their practical applications, and thus, new DPP-4 inhibitors are needed." (PMID 36250007, 2022).
pancreatitis (continued). "Like DPP4 inhibitors, which also target incretin-pathway to lower blood glucose, GLP-1RA use is also associated with increased risk of infections, skin reactions including angioedema and rarely pancreatitis." (PMID 33261058, 2020). "DPP4 inhibitors have been known to cause side effects like skin reactions, angioedema, nasopharyngitis and rarely pancreatitis, which we do not see with metformin." (PMID 33261058, 2020). "A mechanism for pancreatitis during DPP-4 inhibition may be the chronic stimulation of pancreatic acinar and duct cells by GLP-1, since these cells express GLP-1 receptors and proliferate in response to chronic stimulation by GLP-1 in experimental studies." (PMID 31275243, 2019). "Moreover, selective DPP-4 inhibitors have adverse effects related to the immune system such as rheumatoid arthritis and pancreatitis." (PMID 24386644, 2013). "The DPP-4 inhibitors contain no safety information regarding prescribing to patients at risk of pancreatitis." (PMID 23125920, 2012). "Post-marketing surveillance and case reports have identified isolated cases of pancreatitis associated with the use of DPP-4 inhibitors, although some large-scale studies and meta-analyses have not found significantly increased rates of pancreatitis compared to comparators." (PMID 38975525, 2024). "Similarly, a real-world analysis of 225,898 patients showed that the risk for pancreatitis with DPP-4 inhibitors is not higher as with other glucose-lowering drugs." (PMID 31275243, 2019). "Drug-induced pancreatitis has been reported with the use of GLP-1 agonists and dipeptidyl peptidase-4 (DPP-4) inhibitors." (PMID 41531579, 2025). "Because DPP-4 inhibitors elevate the endogenous GLP-1 levels, we also examined the incidence of pancreatitis." (PMID 29507862, 2018). "A meta-analysis that included only type 1 diabetes reported no serious adverse effects closely related to the DPP-4 inhibitors including ketoacidosis and pancreatitis." (PMID 39271520, 2024). "Though many questions have been raised regarding the safety profile of DPP-4 inhibitors particularly in areas of pancreatitis and pancreatic cancer, not much evidence is available for it." (PMID 37287751, 2023). "Since in some studies though, an arithmetically higher incidence of acute (but not chronic) pancreatitis has been found, pancreatitis should be considered in patients with persistent severe abdominal pain (with or without nausea), and DPP-4 inhibitors should be discontinued in such patients." (PMID 31366085, 2019). "If pancreatitis is confirmed, a DPP-4 inhibitor should not be restarted." (PMID 31366085, 2019). "Likewise, no increase of pancreatitis or pancreatic carcinoma was detected in recent large-scale, placebo-controlled, double-blind trials of DPP-4 inhibitors, including SAVOR-TIMI 53 and EXAMINE." (PMID 26137940, 2015). "In addition, DPP-4 inhibitors should not be initiated in a patient with a history of pancreatitis." (PMID 31366085, 2019). "While several studies have reported that the GLP-1 mimetics do not induce pancreatitis in rats, mouse and/or monkey, these studies did not include DPP4 inhibitors, which are the compounds that might be responsible for interactions with pancreatic proteins according to our study." (PMID 25671081, 2013). "The association between pancreatic cancer and GLP-1 RA and DPP-4 inhibitors is not as clear, with some studies showing that they may increase the risk of developing pancreatic cancer due to overstimulation of the GLP-1 receptor and an increased risk of pancreatitis." (PMID 38611003, 2024).